RNU6-997P (RNA, U6 small nuclear 997, pseudogene)
Gene: Small nuclear RNA gene on chromosome 2 (53,570,374 to 53,570,480, reverse strand). Ensembl gene ENSG00000207456.
Homologues: Orthologues: chimpanzee U6 (95% identical), macaque U6 (89% identical), dog U6 (74% identical), pig U6 (74% identical), dog U6 (68% identical). Paralogues in human: RNU6-47P (83% identical), RNU6-33P (82% identical), RNU6-1 (81% identical), RNU6-116P (81% identical), RNU6-15P (81% identical), RNU6-2 (81% identical), RNU6-22P (81% identical), RNU6-30P (81% identical), RNU6-3P (81% identical), RNU6-4P (81% identical), RNU6-5P (81% identical), RNU6-6P (81% identical), and 1286 more.